MPV17 (mitochondrial inner membrane protein MPV17)
Diseases named in the same sentence as MPV17 in open-access papers (continued):
Sharing a sentence is not in itself a finding about the gene and the disease.
peripheral neuropathy (6 papers, 2014 to 2022). A disorder affecting the peripheral nervous system. "With these lines, we examined whether dMpv17 knockdown flies showed neurological defects, such as peripheral neuropathy, seizures, or cognitive disability, that correspond to neurological symptoms of human MPV17-related MDDS." (PMID 36587049, 2022).
tumor (5 papers, 2016 to 2022). "A steady increase in MPV17 expression was observed with increased individual cancer stage, tumor grade, and node metastasis status." (PMID 35919033, 2022). "Taking advantage of The Genome Cancer Atlas (TGCA) database, we show that the abundance of MPV17 transcript is significantly higher in tumours of 10 different tissues, including liver, bile duct, and colon." (PMID 32155188, 2020). "MPV17, as a tumor promoter, could be a new biomarker for LIHC diagnosis and prognosis and probably shed new light on the exploration of LIHC therapies." (PMID 35919033, 2022). "We therefore had to perform this study on unrelated human tumour cells, and it is possible, that the MPV17 protein might localise differently in different cell types." (PMID 26921094, 2016).
cancer (3 papers, 2019 to 2022). A tumor composed of atypical neoplastic, often pleomorphic cells that invade other tissues. "In order to explore the putative role of MPV17 in the control of cancer cell proliferation, we used a loss-of-function approach." (PMID 32155188, 2020). "Mitochondrial inner membrane protein MPV17 is reported to be involved in multiple biological activities of cancers." (PMID 35919033, 2022). "Through the UALCAN database, it was observed that MPV17 had a high expression in most cancers, LIHC included, and it was highly expressed in 371 primary LIHC samples compared to 50 normal tissues." (PMID 35919033, 2022). "Altogether, these results seem to strongly support an involvement of MPV17 in cancer cell proliferation as MPV17 silencing was consistently accompanied by a reduction of both cell proliferation rate and ATF4 protein abundance." (PMID 32155188, 2020). "In this work, the reintroduction of the only known MPV17-coding transcript refuted any role of the protein in cancer cell proliferation." (PMID 32155188, 2020). "Besides, we also performed pathway correlation analysis on MPV17, and it was closely related to the G2M_checkpoint pathway involved in cancer progression." (PMID 35919033, 2022). "In this work we studied the putative role of MPV17 in cancer cell proliferation." (PMID 32155188, 2020). "However, shRNA-mediated MPV17 knockdown performed in this work provided misguiding results regarding the resulting proliferation phenotype and only a rescue experiment was able to shed definitive light on the implication of MPV17 in cancer cell proliferation." (PMID 32155188, 2020). "In conclusion, our work demonstrates that MPV17 does not induce depletion of mtDNA content in cancer cell lines and that MPV17 does not control their cell cycle/proliferation." (PMID 32155188, 2020). "In this study, we show that MPV17 silencing does not induce depletion in mitochondrial DNA content in cancer cells." (PMID 32155188, 2020). "We also show that MPV17 does not control cancer cell proliferation despite the fact that we initially observed a reduced proliferation rate in five MPV17-silenced cancer cell lines with two different shRNAs." (PMID 32155188, 2020). "However, MPV17 silencing did not lead to a reduction of mtDNA content in any of the tested cancer cell lines." (PMID 32155188, 2020). "In this study, while demonstrating that MPV17 does not control neither cell proliferation nor mtDNA content in cancer cells, our experimental results illustrate and emphasize the importance of carrying out a rescue experiment when working with shRNA-mediated knockdown." (PMID 32155188, 2020).
MPV17 also shares sentences with these, for which no sentence is quoted: mitochondrial neurogastrointestinal encephalomyopathy (3 papers); developmental delay (2); Hypertension (2); hypoglycaemia (2); kidney failure (2); microcephaly (2); Ataxia (1); axonal peripheral neuropathies (1); Barth syndrome (1); cholestasis (1); connective tissue diseases (1); Encephalopathy (1); Failure to thrive (1); Friedreich ataxia (1); galactosemia (1); GRACILE syndrome (1); hyperlipidemia (1); inner ear disease (1); kidney disease (1); lactic acidosis (1); Leber hereditary optic neuropathy (1); Leigh syndrome (1); Leukoencephalopathy (1); liver cancer (1); lysosomal storage disorders (1); metabolic disease (1); myopathy (1); Niemann-Pick disease type C (1); Nystagmus (1); osteosarcoma (1).
A further 6 diseases each share a sentence with MPV17 in 1 paper.